SPANXA2 (SPANX family member A2)
Synonyms: CT11.1; SPANX-A; SPANXA; SPANX
Gene: Protein-coding gene on chromosome X (141,589,708 to 141,590,762, forward strand). Ensembl gene ENSG00000203926.
Subcellular location: Cytoplasm; Nucleus
Subcellular location (Human Protein Atlas): Nucleoplasm; Vesicles
Gene Ontology:
Molecular function: protein binding
Biological process: spermatogenesis
Cellular component: nucleus; cytoplasm
Homologues: Paralogues in human: SPANXA1 (100% identical), SPANXC (94% identical), SPANXD (94% identical), SPANXB1 (85% identical).
Diseases named in the same sentence as SPANXA2 in open-access papers:
SPANXA2 is named in the same sentence as 1 disease in open-access papers, as found by Europe PMC text mining. Sharing a sentence is not in itself a finding about the gene and the disease.
SPANXA2 shares sentences with these, for which no sentence is quoted: cervical cancer (1 paper).